ARID1A (AT-rich interaction domain 1A)
Diseases named in the same sentence as ARID1A in open-access papers (continued):
Sharing a sentence is not in itself a finding about the gene and the disease.
endometriosis (continued). "The association between endometriosis and ARID1A mutation indicates that seromucinous tumors are a type of ERON, along with endometrioid and clear cell tumors." (PMID 32023964, 2020). "Potential oncogenic mutations found included PIK3CA, KRAS, PIK3R1, and FGFR2 in benign epithelial endometrium from women with uterine fibroids, and ARID1A mutations in endometrial stroma from women with endometriosis." (PMID 31717878, 2019). "Endometrioid carcinoma and clear cell carcinoma are caused by endometriosis or endometriosis-related ovarian neoplasms, and these often have ARID1A and PIK3CA mutations." (PMID 31623180, 2019). "Using the monoclonal EPR13501 antibody, which had the best inter‐rater agreement in our study, would allow comprehensive analysis of endometriosis to determine the clinical significance of ARID1A loss and be of potential diagnostic use." (PMID 29659191, 2018). "Somatic inactivating mutations of ARID1A and loss of ARID1A expression appear to be an early event in the development of most ovarian clear cell and endometrioid carcinomas as well as atypical endometriosis." (PMID 29451900, 2018). "Mutations in KRAS and ARID1A have been discovered in endometriosis, including ovarian endometriosis and deep infiltrating endometriosis." (PMID 30087267, 2018). "Loss of ARID1A was quite frequent (76.9%, 20/26) in clear cell carcinoma with concurrent endometriosis." (PMID 29743986, 2018). "Loss of ARID1A is more frequent in endometriosis associated neoplasms, with loss of ARID1A immunohistochemical expression in 61% of endometriosis associated clear cell carcinomas." (PMID 29093822, 2017). "These cancers have been molecularly and epidemiologically linked to endometriosis with approximately 20% of benign ovarian endometriosis lesions having a loss of BAF250a (encoded by ARID1A) expression." (PMID 27979878, 2017). "Taken together, these data strongly support a model for early mutation of ARID1A during malignant transformation of endometriosis." (PMID 26456077, 2016). "Particularly, activation of oncogenic KRAS and PI3K pathways and inactivation of tumor suppressor genes PTEN and ARID1A are suggested as major pathogenic mechanisms for endometriosis associated clear-cell and endometrioid ovarian cancer." (PMID 26413541, 2015). "Mutations of ARID1A have been demonstrated in atypical endometriosis, indicating the fact that ARID1A mutations are an early event in the pathogenesis of EAOC." (PMID 26413541, 2015). "Determining the mechanism of Arid1a in uterine dysfunction associated with infertility and endometriosis will be critical to understanding both of these common uterine diseases for future therapy." (PMID 26378916, 2015). "AT-rich interactive domain 1A gene (ARID1A) loss is a frequent event in endometriosis-associated ovarian carcinomas." (PMID 26378916, 2015). "ARID1A mutations were found in the primary malignant lesion and the contiguous, atypical endometriosis." (PMID 23466883, 2013). "The transition from atypical endometriosis to CCOC is facilitated by the disruption of chromatin remodeling caused by loss of ARID1A function, which results in aberrant transcription of tumor suppressor genes, enhanced cell proliferation, and resistance to apoptosis." (PMID 41465243, 2025). "Loss of ARID1A function is considered an early event in the malignant transformation of endometriotic tissue and may occur independently of the atypical endometriosis phenotype." (PMID 41465243, 2025). "PTEN loss may be an early event in cancer development from endometriosis, as well as genetic mutations affecting ARID1A and PIK3CA seem to play a role." (PMID 38438776, 2024). "Further common driver mutations in endometriosis include ARID1A, PIK3CA, and PPP2R1A." (PMID 38673891, 2024). "ARID1A mutation seems to be an early event also in endometrial glandular epithelium malignant transformation and ARID1A loss was found in areas with atypical endometriosis." (PMID 36890819, 2023).
endometriosis (continued). "Importantly, the correlation between ARID1A loss and worse outcome remained significant even after adjusting for stage and endometriosis in multivariate analysis (PFS, P = 0.004; CSS, P < 0.001; OS, P < 0.001)." (PMID 36082022, 2022). "Furthermore, studies using mouse models have shown that deletion of uterine Arid1a drives increased endometriosis-like lesion establishment and causes endometrial-factor infertility related to disrupted P4 and E2 signaling." (PMID 35682747, 2022). "Notably, we found that loss of ARID1A occurred more frequently in patients with endometriosis found during pathologic diagnosis, and also had a tendency to present at lower stages." (PMID 36082022, 2022). "It has been reported that the complement system is activated in women with endometriosis, suggesting that ARID1A mutation and associated disruption of chromatin repression may be a possible disease mechanism." (PMID 36153585, 2022). "However, there is still controversy existing at which stage of endometriosis ARID1A mutation does occur." (PMID 36612107, 2022). "Next, ARID1A heterozygous mutation occurs in the process of endometriosis development and second hit of ARID1A such as genomic or epigenetic alteration leads to malignant transformation of endometriosis." (PMID 33809880, 2021). "Several studies have found ARID1A mutations and loss of expression of BAF250a in endometriosis adjacent to EC hypothesizing that this alteration may occur early in precursor lesions." (PMID 33919741, 2021). "A study including 54 patients demonstrated a progressive increase in ARID1A protein expression loss from normal endometrium (0%), to typical endometriosis (19%), to atypical endometriosis (38%), further supporting that ARID1A loss is an early event in OCCC pathogenesis." (PMID 34659566, 2021). "Moreover, ARID1A protein expression was retained in all benign endometriosis samples with ARID1A loss-of-function mutations." (PMID 32868822, 2020). "Some deep infiltrating endometriosis cases also harbor ARID1A mutations." (PMID 32868822, 2020). "Interestingly, ovarian endometriosis patients with ARID1A loss-of-function mutations had a higher frequency of endometriosis lesions in bilateral ovaries (P = 0.006)." (PMID 32868822, 2020). "In other words, the “two-hit” hypothesis can explain why ARID1A protein expression was retained in all benign endometriosis samples with ARID1A loss-of-function mutations and a portion of clear cell carcinoma with ARID1A loss-of-function mutations." (PMID 32868822, 2020). "Importantly, ARID1A mutation and protein loss are also identified in atypical endometriosis adjacent to clear cell carcinoma, which suggests that this abnormality is an early event in endometriosis-related carcinogenesis." (PMID 32023964, 2020). "The association of ARID1A protein expression with ARID1A mutations in benign endometriosis remains unclear." (PMID 32868822, 2020). "The results suggest that the loss of ARID1A expression and ARID1A mutations in endometriosis may be involved in the development of ERONs." (PMID 31126056, 2019). "This study identified mutations in the ARID1A gene in ovarian clear cell and endometrioid carcinomas; these results represent that mutations in ARID1A are an early event in the malignant transformation of endometriosis." (PMID 29780815, 2018). "Apparently, oxidative stress suppresses ARID1A expression in endometriotic cells; conversely, the low ARID1A gene activity occurring in endometriosis could increase the susceptibility of these lesions to malignant transformation." (PMID 29743986, 2018). "Also, ARID1A gene mutations were described for endometriosis-associated endometrioid and clear cell cancers." (PMID 28086974, 2017). "Two of the patients who had OCCA samples with ARID1A mutations also had contiguous atypical endometriosis (ie with epithelial cells showing nuclear enlargement, crowding, slight hyperchromasia, and possible chromocentres/nucleoli and/or architectural abnormalities)." (PMID 26456077, 2016).
endometriosis (continued). "Determining the role of Arid1a in stromal-epithelial cross talk will be critical in understanding the role of steroid hormone signaling and dysfunction associated with infertility and endometriosis." (PMID 26378916, 2015). "Somatic ARID1A mutations are uniquely associated with endometriosis-related ovarian neoplasms." (PMID 26378916, 2015). "ARID1A mutations which occur randomly in the coding regions, the great majority being frameshift and nonsense, leading to lost expression of ARID1A, are found in preneoplastic lesions of endometrial tissue, suggesting a pivotal role in the potential transformation of endometriosis into cancer." (PMID 39859551, 2025). "Emerging evidence suggests that ARID1A mutation may represent an early event in the malignant transformation of endometrial glandular epithelium, and loss of ARID1A expression has also been observed in areas of atypical endometriosis." (PMID 41465243, 2025). "Furthermore, studies discovered that ARID1A mutations and loss of BAF250a protein accumulated in a stepwise manner during the transformation process from benign endometriosis through atypical endometriosis to OCCC, suggesting that ARID1A mutation occurred as a very early event in OCCC development." (PMID 36873929, 2023). "In particular, a splice site mutation of ARID1A was shared among the uterine endometrium, distant endometriosis, adjacent endometriosis, and clear cell carcinoma, whereas another frameshift mutation was specific to the adjacent endometriosis site and the carcinoma." (PMID 33809880, 2021). "Therefore, in women with endometriosis and high levels of miR-221 and miR-222, the loss of ARID1A expression could determine the progression to ERON." (PMID 31126056, 2019). "The frequency of loss of ARID1A expression in the endometriosis lesions is an ongoing concern in many studies, as it is suspected that it might be the major genetic alteration that determines the evolution of endometriosis to malignancy." (PMID 31126056, 2019). "The findings incriminate ARID1A, PgE2 synthase, and PgE2-Rec as potential markers for malignant transformation in endometriosis, especially in the ovarian tissue." (PMID 40364006, 2025). "Research should also focus on efficacy of targeted therapies based on ARID1A and PIK3CA mutations for endometriosis-associated OCCC." (PMID 41244554, 2025). "OCCC is characterized by distinct clinicopathological features and molecular alterations, frequently harboring somatic mutations in ARID1A, PIK3CA, and the TERT promoter (TERTp), often in association with endometriosis." (PMID 40862791, 2025). "EC, often found at stage I, has a good prognosis, is linked to endometriosis, and commonly involves mutations in CTNNB1, PIK3CA, ARID1A, and PTEN." (PMID 41375063, 2025). "Endometriosis demonstrates a significant genetic basis, with mutations in specific genes, including KRAS, PTEN, and ARID1A, actively being researched to comprehend their association with the increased risk of developing DE." (PMID 39859551, 2025). "ARID1A mutations, frequently seen in both OEC and OCCC, are known to be a hallmark of endometriosis-associated ovarian cancers." (PMID 41425725, 2025). "CCC, with its glycogen-rich, clear cytoplasm, has a poor prognosis even when caught early, is sometimes connected to endometriosis, and frequently shows mutations in PIK3CA, ARID1A, and PPP2R1A." (PMID 41375063, 2025). "Advances in the SWI/SNF complex and ARID1A alterations provide insights into endometriosis and EAOC carcinogenesis." (PMID 38610698, 2024). "It was reported that ARID1A mutations and loss of BAF250a expression were often evident in OCCC tumors and contiguous atypical endometriosis instead of distant endometriotic lesions." (PMID 36873929, 2023).
endometriosis (continued). "In addition, the loss of ARID1A has been demonstrated in patient samples with atypical endometriotic lesions contiguous to clear-cell OC, raising the possibility that the loss of ARID1A may contribute to an early cancer-promoting event in endometriosis that leads to clear-cell OC." (PMID 37109525, 2023). "Clear cell carcinomas frequently present with variants in ARID1A and PIK3CA, which have been found in adjacent endometriosis variants." (PMID 38132375, 2023). "Downregulation of ARID1A has been reported already at the level of endometriosis, and in one study, this was attributed to hypermethylation of the gene promoter." (PMID 37627318, 2023). "Synchronous alterations in mTOR signaling and ARID1A expression are highly frequent in EAOCs and their precursor endometriosis lesions, reinforcing the idea that both genetic events promote EAOC development in a synergistic manner." (PMID 37627318, 2023). "The cancer is characterized by frequent inactivation of ARID1A and 10% of cases of endometriosis progression to OCCC." (PMID 37087441, 2023). "We previously showed that endometrial ARID1A levels are diminished in women with endometriosis and that abolishing endometrial epithelial ARID1A expression drives a loss of endometrial receptivity and failure of pregnancy establishment and maintenance." (PMID 35682747, 2022). "Endometrial epithelial ARID1A is indispensable for pregnancy establishment in mice through regulation of endometrial gland function; however, ARID1A expression is decreased in infertile women with endometriosis." (PMID 35682747, 2022). "Most notably, ARID1A in endometriosis-related OC, SMARCA4, and SMARCB1 in hypercalcemic type small cell ovarian carcinoma (SCCOHT), ACTL6A, CHRAC1, RSF1 amplification in high-grade serous OC." (PMID 36430148, 2022). "All of the 6 PIK3CA-mutation-positive typical endometriosis (TE) were immunohistochemically ARID1A deficient; at the same time, all of the 6 AE harboring PIK3CA mutations were ARID1A deficient." (PMID 35457244, 2022). "Somatic mutations such as ARID1A, PTEN, and PIK3CA have been reported in patients displaying atypical endometriosis and development of endometrioid and clear cell carcinomas." (PMID 34454550, 2021). "Next, Western blot analysis and immunohistochemistry showed that the protein expression of ARID1A in endometriosis tissues was strikingly lower than that in normal tissues." (PMID 34586697, 2021). "Genetic mutations in ARID1A, K-RAS, PTEN, and β-catenin/Wnt and microsatellite instability are also considered as important factors for the progression of endometriosis to EAOC." (PMID 33803806, 2021). "Correlation map drawn based on analysis in microarray dataset GSE37837 revealed a positive correlation between HNF4A and ARID1A expression in endometriosis tissues." (PMID 34586697, 2021). "Of particular note, the ARID1A gene is thought to be involved in the progression of endometriosis to carcinoma." (PMID 34150634, 2021). "Intriguingly, ARID1A downregulation has been elaborated to be involved in the pathogenesis of endometriosis." (PMID 34586697, 2021). "Known somatic cancer-driver mutations in ARID1A, PIK3CA, and KRAS have been identified in deep endometriosis, indicating that endometriosis is a neoplastic disease." (PMID 34067626, 2021). "We have reported a variety of molecular events such as ARID1A mutations, PIK3CA mutations, MET activation, HNF-1β activation, and miRNA dysfunction in endometriosis-associated OCCC." (PMID 34659566, 2021). "Recent research suggest that many putative driver genes and aberrant pathways including ARID1A mutations, PIK3CA mutations, MET activation, HNF-1β activation, and miRNAs dysfunction, play crucial roles in the malignant transformation of endometriosis to OCCC." (PMID 34659566, 2021). "Mutations in ARID1A gene have been demonstrated in approximately half of all ovarian CCC, as well as in areas of atypical endometriosis associated with these tumors." (PMID 33919741, 2021).
endometriosis (continued). "In particular, some studies report that ARID1A and PIK3CA mutations are more frequent in CCC endometriosis-associated, whereas they are less common in tumors with adenofibromatous component." (PMID 33919741, 2021). "When ARID1A was knocked down in endometriosis cells, AMPK‐Thr172 phosphorylation was elevated, as shown in western blot analysis." (PMID 33331115, 2021). "Moreover, oxidative stress appears to be able to decrease the expression of ARID1A protein and mRNA levels in endometriotic cells, and low ARID1A gene activity in endometriosis may be a predisposing factor for the increased susceptibility of these lesions to the malignant transformation." (PMID 34659566, 2021). "The ARID1A, PI3K/AKT/mTOR, MET, and HNF-1β pathways are frequently activated and are considered promising targets for the treatment of endometriosis-associated OCCC." (PMID 34659566, 2021). "Conclusively, the activation of the HNF4A/ARID1A axis inhibited the proliferation and invasion and promoted the apoptosis of endometriosis cells." (PMID 34586697, 2021). "Mutations in tumor suppressor genes such as ARID1A and PIKA3CA have been found in patients with both endometriosis and an endometriosis-related cancer." (PMID 32033052, 2020). "Studies have shown that ARID1A has a crucial role in implantation and decidualization, since ARID1A expression is lost in endometriosis." (PMID 32183093, 2020). "Evidence showing direct binding of ARID1A to PR-A as well as loss of P4 signaling in mice with conditional ablation of Arid1a in the uterus implicates the decrease of ARID1A in endometriosis in the P4 resistance phenotype as well." (PMID 31387263, 2019). "This study clearly demonstrated described mutations in contiguous endometriosis shared by EAOC, and even some distant lesions contained the same (PIK3CA and ARID1A) mutations." (PMID 29456620, 2018). "Common genetic alterations, particularly in ARID1A, have been recognized within atypical endometriosis and adenocarcinoma, suggesting a significant carcinogenic role." (PMID 29093822, 2017). "The second way was genetic mutations in endometriosis tissues, such as hepatocyte nuclear factor-1β (HNF-1β) and ARID1A." (PMID 27854255, 2016). "Further investigation of ARID1A will be important for understanding altered endometrial function in infertility and endometriosis and in developing therapies for these disorders." (PMID 26378916, 2015). "In conclusion, ARID1A has a key role in implantation and decidualization, and that ARID1A expression is lost in endometriosis." (PMID 26378916, 2015). "Loss of BAF250a, a tumor suppressor protein that is associated with ARID1A, is an early event in the process of malignant transformation, seen in contiguous endometriosis lesions but not in distant foci." (PMID 40364006, 2025). "ARID1A mutations, along with PI3K/Akt and mTOR pathway disturbances and epigenetic changes, may contribute to the malignant transformation of endometriosis." (PMID 41465243, 2025). "Loss of ARID1A expression playing an important role in the malignant process of endometriosis, a study also found that partial loss of ARID1A expression was detected in ovarian endometriosis, DIE, and endometriosis in pelvic sentinel lymph nodes." (PMID 41013561, 2025). "In another investigation, a partial loss of BAF250a (ARID1A) expression was exhibited in 36% of the cases of rectovaginal deep infiltrating endometriosis (DIE), 40% of endometriosis lesions in pelvic sentinel lymph nodes (PSLNs), 30% of ovarian endometriomas, and 25% of control endometrium samples." (PMID 40364006, 2025). "Mutations in ARID1A, PIK3CA, and PTEN may drive the progression from benign endometriosis to cancer." (PMID 40508002, 2025).